ZSCAN4 (zinc finger and SCAN domain containing 4)
Description:
Embryonic stem (ES) cell-specific transcription factor required to regulate ES cell pluripotency. Binds telomeres and plays a key role in genomic stability in ES cells by regulating telomere elongation. Acts as an activator of spontaneous telomere sister chromatid exchange (T-SCE) and telomere elongation in undifferentiated ES cells (By similarity).
Synonyms: ZNF494; FLJ35105
Tractability: No criterion of Open Targets' tractability assessment is met for any kind of drug.
Gene: Protein-coding gene on chromosome 19 (57,668,935 to 57,679,152, forward strand). Ensembl gene ENSG00000180532.
Subcellular location: Nucleus; Chromosome, telomere
Pathways (Reactome):
Developmental Biology: Zygotic genome activation (ZGA)
Gene Ontology:
Molecular function: protein binding; sequence-specific double-stranded DNA binding; DNA-binding transcription factor activity, RNA polymerase II-specific; RNA polymerase II cis-regulatory region sequence-specific DNA binding
Biological process: negative regulation of mitotic recombination; regulation of transcription by RNA polymerase II; telomere maintenance via telomere lengthening
Cellular component: chromosome, telomeric region; nucleus
Genetic constraint (gnomAD): Loss-of-function variants: 18 observed, 17.89 expected, observed/expected ratio (o/e) 1.01, 90% interval 0.69 to 1.49. The upper end of that interval is the gene's LOEUF score, 1.49, which puts it in group 6 of 6, group 1 being the genes least tolerant of losing a copy. Missense variants: 498 observed, 533.13 expected, observed/expected ratio (o/e) 0.93, 90% interval 0.87 to 1.01. Synonymous variants: 193 observed, 186.94 expected, observed/expected ratio (o/e) 1.03, 90% interval 0.92 to 1.16.
Homologues: Orthologues: chimpanzee ZSCAN4 (98% identical), macaque ZSCAN4 (90% identical). Paralogues in human: ZKSCAN3 (21% identical), ZNF397 (20% identical), ZKSCAN4 (20% identical), ZNF500 (20% identical), ZKSCAN8 (20% identical), ZKSCAN1 (19% identical), ZNF263 (19% identical), ZSCAN25 (19% identical), ZNF75A (19% identical), ZSCAN12 (19% identical), ZSCAN30 (19% identical), ZSCAN31 (19% identical), and 18 more.